SHLD1 (shieldin complex subunit 1)
Description:
Component of the shieldin complex, which plays an important role in repair of DNA double-stranded breaks (DSBs). During G1 and S phase of the cell cycle, the complex functions downstream of TP53BP1 to promote non-homologous end joining (NHEJ) and suppress DNA end resection. Mediates various NHEJ-dependent processes including immunoglobulin class-switch recombination, and fusion of unprotected telomeres.
Synonyms: C20orf196; RINN3; FLJ25067
Tractability: PROTAC: ubiquitination databases record sites on it.
Gene: Protein-coding gene on chromosome 20 (5,750,372 to 5,864,395, forward strand). Ensembl gene ENSG00000171984.
Subcellular location: Chromosome
Subcellular location (Human Protein Atlas): Endoplasmic reticulum; Golgi apparatus; Vesicles
Gene Ontology:
Molecular function: protein binding
Biological process: negative regulation of double-strand break repair via homologous recombination; positive regulation of double-strand break repair via nonhomologous end joining; positive regulation of isotype switching; somatic diversification of immunoglobulins involved in immune response; telomere maintenance in response to DNA damage; regulation of double-strand break repair via nonhomologous end joining
Cellular component: chromosome; site of double-strand break; chromatin
Genetic constraint (gnomAD): Loss-of-function variants: 3 observed, 7.15 expected, observed/expected ratio (o/e) 0.42, 90% interval 0.19 to 1.08. That is too few expected variants to judge how well the gene tolerates losing a copy. Missense variants: 203 observed, 245.33 expected, observed/expected ratio (o/e) 0.83, 90% interval 0.74 to 0.93. Synonymous variants: 90 observed, 95.26 expected, observed/expected ratio (o/e) 0.94, 90% interval 0.8 to 1.13.
Homologues: Orthologues: chimpanzee SHLD1 (97% identical), macaque SHLD1 (93% identical), dog SHLD1 (76% identical), pig SHLD1 (73% identical), rabbit SHLD1 (73% identical), guinea pig SHLD1 (64% identical), mouse Shld1 (64% identical), rat Shld1 (63% identical).
Diseases named in the same sentence as SHLD1 in open-access papers:
SHLD1 is named in the same sentence as 8 diseases in open-access papers, as found by Europe PMC text mining. Sharing a sentence is not in itself a finding about the gene and the disease. The quoted sentences say what the papers report.
breast cancer (3 papers, 2022 to 2024). A primary or metastatic malignant neoplasm involving the breast. "Loss of 53BP1 and reduced SHLD1/2 expression has been identified in patient-derived tumour models of PARPi-resistant breast cancer." (PMID 37430137, 2023). "Among PDXs from patients with germline BRCA1/2-mutated breast cancer, 2 of 9 PARPi-resistant models had somatic mutations in TP53BP1 and exposure to olaparib in PDX models correlated with reduced mRNA expression of SHLD1 and SHLD2." (PMID 37430137, 2023).
Parasitemias (2 papers, 2012 to 2016). "By light microscopy, 3D7-PfMOP-DD parasites with or without Shld1 develop from early ring-stages to multi-nucleated schizonts without loss of parasitemia within the development cycle." (PMID 27121004, 2016). "Notably, the schizont parasitemia was similar for all Shld1 conditions." (PMID 27121004, 2016). "Parasitemias of the cultures kept at 0.5 μM and 1.0 μM Shld-1 were reduced by 11% and 18% after the first reinvasion cycle (48 hours) and by 25% and 45% after the second cycle, respectively, compared to no Shld-1 controls." (PMID 22815885, 2012).
B cell lymphoma (1 paper, 2024). "For this, we introduced TwinStrep-tagged Shld1 and Shld3 transgenes into Shld1−/− and Shld3−/− CH12-F3 mouse B cell lymphoma cell lines, respectively, and validated functional complementation at the level of rescued IgM-to-IgA class switching in stimulated cell cultures." (PMID 39227718, 2024).
glioma (1 paper, 2024). A benign or malignant brain and spinal cord tumor that arises from glial cells (astrocytes, oligodendrocytes, ependymal cells). "Similar survival trends were observed for TRIP13 and SHLD1 expression in low grade glioma patients receiving TMZ." (PMID 38906885, 2024).
infection (2 papers, 2010 to 2014). The state of being infected such as from the introduction of a foreign agent such as serum, vaccine, antigenic substance or organism. "We predicted that infection would be pUL117-deficient without Shld1 (pFKBP-UL117 unstable) but would be wild type with Shld1 (pFKBP-UL117 stable)." (PMID 20333247, 2010). "Here, we infected HFF cells with ADddUL79 in the presence or absence of Shld1, and analyzed infected cell lysates by immunoblotting at various times post infection." (PMID 25166009, 2014).
tumor (2 papers, 2015 to 2024). "Thus, Shld1 can be used to fine tune PTEN activity to inhibit tumor growth and tumor cell division." (PMID 26717575, 2015).
cancer (1 paper, 2024). A tumor composed of atypical neoplastic, often pleomorphic cells that invade other tissues. "Recent studies have shown that, in human cancer cells, the tetrameric Shieldin complex (comprising REV7, SHLD1, SHLD2, and SHLD3) facilitates non-homologous end-joining (NHEJ) while blocking homologous recombination (HR)." (PMID 39630591, 2024).
SHLD1 also shares sentences with these, for which no sentence is quoted: depression (1 paper).